RNU2-33P (RNA, U2 small nuclear 33, pseudogene)
Gene: Small nuclear RNA gene on chromosome 14 (96,384,624 to 96,384,815, forward strand). Ensembl gene ENSG00000222276.
Homologues: Orthologues: chimpanzee U2 (99% identical), macaque U2 (92% identical), guinea pig U2 (73% identical), guinea pig U2 (67% identical), pig U2 (66% identical), rabbit U2 (48% identical), rabbit U2 (46% identical). Paralogues in human: RNU2-48P (83% identical), U2 (81% identical), U2 (80% identical), RNU2-64P (78% identical), RNU2-8P (78% identical), RNU2-59P (78% identical), RNU2-23P (77% identical), RNU2-4P (77% identical), RNU2-56P (77% identical), RNU2-61P (77% identical), RNU2-15P (77% identical), RNU2-2 (77% identical), and 65 more.